SLC30A4 (solute carrier family 30 member 4)
Description:
Probable proton-coupled zinc ion antiporter mediating zinc import from cytoplasm potentially into the endocytic compartment. Controls zinc deposition in milk (By similarity).
Synonyms: ZnT-4; ZNT4
Tractability: Antibody: UniProt places it where antibodies can reach, with medium confidence; UniProt predicts a signal peptide or a membrane-spanning region; its Gene Ontology location is reachable by antibodies, with medium confidence. PROTAC: ubiquitination databases record sites on it.
Gene: Protein-coding gene on chromosome 15 (45,479,606 to 45,522,829, reverse strand). Ensembl gene ENSG00000104154.
Subcellular location: Endosome membrane; Late endosome membrane; Lysosome membrane; Cytoplasm
Gene Ontology:
Molecular function: protein binding; zinc ion transmembrane transporter activity; monoatomic cation transmembrane transporter activity
Biological process: response to toxic substance; zinc ion import into lysosome; zinc ion transmembrane transport; response to zinc ion; monoatomic cation transport; otolith development; swimming behavior; transmembrane transport; zinc ion import into organelle
Cellular component: cytoplasm; late endosome; lysosomal membrane; plasma membrane; transmembrane transporter complex; vesicle membrane; endosome membrane; cytoplasmic vesicle; late endosome membrane; membrane
Genetic constraint (gnomAD): Loss-of-function variants: 6 observed, 17.45 expected, observed/expected ratio (o/e) 0.34, 90% interval 0.19 to 0.68. The upper end of that interval is the gene's LOEUF score, 0.68, which puts it in group 2 of 6, group 1 being the genes least tolerant of losing a copy. Missense variants: 275 observed, 316.98 expected, observed/expected ratio (o/e) 0.87, 90% interval 0.79 to 0.96. Synonymous variants: 111 observed, 128.01 expected, observed/expected ratio (o/e) 0.87, 90% interval 0.74 to 1.01.
Homologues: Orthologues: chimpanzee SLC30A4 (99% identical), macaque SLC30A4 (99% identical), pig SLC30A4 (95% identical), dog SLC30A4 (95% identical), rabbit SLC30A4 (95% identical), mouse Slc30a4 (92% identical), rat Slc30a4 (91% identical), guinea pig SLC30A4 (69% identical), tropical clawed frog slc30a4 (66% identical), zebrafish slc30a4 (42% identical), Caenorhabditis elegans ttm-1 (33% identical), Drosophila melanogaster ZnT41F (30% identical). Paralogues in human: SLC30A2 (34% identical), SLC30A8 (32% identical), SLC30A3 (30% identical), SLC30A1 (19% identical), SLC30A5 (19% identical), SLC30A10 (19% identical), SLC30A7 (16% identical), SLC30A6 (15% identical).
Diseases named in the same sentence as SLC30A4 in open-access papers:
SLC30A4 is named in the same sentence as 19 diseases in open-access papers, as found by Europe PMC text mining. Sharing a sentence is not in itself a finding about the gene and the disease. The quoted sentences say what the papers report.
prostate carcinoma (8 papers, 2020 to 2025). A carcinoma that arises from epithelial cells of the prostate gland. "SLC30A4 encodes Zinc transporter 4 (hZnT-4) that is a potential target of micro RNA MiR-452-5p that has been associated with the development of prostate cancer." (PMID 32584883, 2020). "Our data demonstrated that expression of SLC30A4 was predominantly evident in prostate epithelial cells, suggesting, the altered expression of the gene in prostate cancer likely is an epithelial cell event." (PMID 32584883, 2020). "And SLC30A4 was overexpressed in prostate cancer compared to paracancerous tissues, and SLC30A4 was negatively correlated with the intensity of immunoreactivity in prostate cancer." (PMID 35154468, 2022).
Zinc deficiency (6 papers, 2011 to 2024). A deficiency of the essential metal Zinc; an essential cofactor for many enzymes. "Furthermore, Slc30a4 is needed for zinc uptake and transport and zinc deficiency leads to placental Lz malformations, including a thinner barrier for diffusion and fetal growth retardation." (PMID 38671859, 2024).
cervical cancer (1 paper, 2022). A primary or metastatic malignant neoplasm involving the cervix. "For tumor stages, SLC30A1, SLC30A7 and SLC30A10 groups significantly varied, whereas SLC30A2, SLC30A3, SLC30A4, SLC30A5, SLC30A6, SLC30A8 and SLC30A9 did not significantly differ in cervical carcinoma." (PMID 35154468, 2022). "However, the expression of SLC30A3, SLC30A4, SLC30A5, SLC30A6 and SLC30A9 genes in cervical cancer was not statistically significant compared to the corresponding paracancerous tissues." (PMID 35154468, 2022).
gastric adenocarcinoma (1 paper, 2023). "In addition, we found that the expression levels of SLC30A1, SLC30A5, SLC30A6 and SLC30A7 were significantly elevated, while the expression level of SLC30A4 was significantly decreased in gastric adenocarcinoma tissues compared with both normal gastric tissues and matched normal gastric tissues." (PMID 37524874, 2023).
gastric cancer (1 paper, 2020). A primary or metastatic malignant neoplasm involving the stomach. "We found that the median expression levels of SLC30A1-3, 5–7, and 9 were significantly upregulated in gastric cancer tissues compared to non-cancerous tissues, while SLC30A4 was downregulated." (PMID 33110097, 2020). "In the present study, mRNA expression of SLC30A1-3, SLC30A5-7, and 9 was significantly upregulated in gastric cancer tissues compared to non-cancer tissues in GC patients, while SLC30A4 was downregulated in cancer tissues." (PMID 33110097, 2020).
tumor (3 papers, 2016 to 2025). "SLC30A4 and SLC39A8 act as tumor suppressors in a context-dependent manner." (PMID 41583444, 2025).
infection (1 paper, 2023). The state of being infected such as from the introduction of a foreign agent such as serum, vaccine, antigenic substance or organism. "In apparent contrast to the observation that in the late stages of infection the bacteria are under zinc starvation, gene expression data revealed elevated transcription of slc30a1a and slc30a4 even at 48 hpi." (PMID 36674459, 2023). "At the same time, zebrafish respond to the infection by activating the expression of the Zn transporters Slc30a1 and Slc30a4, whose mammalian homologs mediate a redistribution of Zn in phagocytes aimed at intoxicating bacteria with a metal excess." (PMID 36674459, 2023). "Our results show that the expression levels of slc30a1a and slc30a4 are significantly increased in zebrafish upon P. aeruginosa infection, suggesting that they have a role in controlling infections through mechanisms involving Zn redistribution in phagocytes, as observed in mammals." (PMID 36674459, 2023).
SLC30A4 also shares sentences with these, for which no sentence is quoted: cancer (2 papers); Cognitive impairment (2); depression (2); asthenozoospermia (1); asthma (1); bacterial infection (1); Crohn disease (1); gastric tumor (1); inflammation (1); ischemic stroke (1); metastatic disease (1); Obesity (1).